INS (insulin)
Diseases named in the same sentence as INS in open-access papers (continued):
Sharing a sentence is not in itself a finding about the gene and the disease.
Hyperglycemia (continued). "Hyperglycemia makes people lose weight because they eat more fats and structural proteins than carbs, and carbohydrates are used and controlled by insulin." (PMID 36983154, 2023). "Hyperglycemia influences the insulin-sensitive channels on cell surfaces, significantly decreasing the abundance of glucose transporters, specifically glucose transporter type 4." (PMID 37893045, 2023). "Due to delays in insulin absorption compared with meal glucose absorption, this approach resulted in prolonged postprandial hyperglycemia." (PMID 38057844, 2023). "It is a metabolic disorder characterized by hyperglycemia resulting from either insufficient insulin secretion or ineffective insulin action." (PMID 37674617, 2023). "Unfortunately, the clinical findings about hyperglycaemia treatment in patients with pheochromocytoma are scarce, and only a few case reports show a good glycaemic control obtained with metformin or insulin." (PMID 37842314, 2023). "DM is characterized by long-standing hyperglycemia due to defective insulin secretion, impairment of the biological action of insulin, or both." (PMID 37106471, 2023). "The keywords used in the search were "Telemedicine" AND "Hyperglycemia" AND ("Diabetic Patients") AND ("Insulin Therapy" OR "Insulin Treatment") AND ("Primary Care" OR "Primary Healthcare") AND "RCT"." (PMID 38077677, 2023). "In isolated IGT, on the other hand, muscle insulin resistance and a defect in the second phase of insulin secretion result in long-term hyperglycemia." (PMID 37049479, 2023). "The liver, as an important insulin-sensitive tissue, is one of the primary organs vulnerable to the oxidative stress induced by hyperglycemia, which ultimately results in liver tissue injury." (PMID 37970436, 2023). "The basal dose is administered 2 h before the insulin infusion is stopped to prevent rebound hyperglycemia." (PMID 37120562, 2023). "In STZ-treated rats, which present hyperglycemia and low insulin, autophagy proteins (LC3, ATG5, ATG12, and BECN1) were significantly elevated in the gastrocnemius muscle, which contributed to the increase of p-FOXO3a and the subsequent repression of mTOR." (PMID 37876013, 2023). "Reduced insulin sensitivity has been demonstrated in cord blood of infants exposed to maternal hyperglycemia." (PMID 37409227, 2023). "Clinical trials using acarbose and miglitol as α-glycosidase inhibitors have revealed lower postprandial hyperglycemia and greater insulin sensitivity." (PMID 36838726, 2023). "Inhibition of DPP-IV regulates insulin secretion, resulting in reduced postprandial and fasting hyperglycemia." (PMID 36839313, 2023). "The main effect of GLP-1 is the enhancement of insulin secretion from beta-cells in response to hyperglycemia and the inhibition of the release of glucagon from alpha cells." (PMID 36675217, 2023). "A retrospective study reported that patients treated with SC insulin had more hyperglycaemias (52.2% vs 35.8%) but also more frequent hypoglycaemias (2.1% vs 1.2%) than those treated with IV insulin." (PMID 37330419, 2023). "The reversible crosslinkages between catechol and boronate decrease with increasing glucose concentration leading to higher swelling and faster insulin release at hyperglycemia as compared to euglycemia." (PMID 37718654, 2023). "Diabetic mice were confirmed with severe hyperglycemia during the entire experiment and eventually needed assistance with insulin therapy to maintain their wellbeing." (PMID 36830829, 2023). "β-cells become dysfunctional and fail to secrete adequate amounts of insulin, leading to hyperglycemia." (PMID 37240215, 2023). "Co‐existence of hypoglycemias and hyperglycemias has been reported in patients with loss‐of‐function ABCC8 hyperinsulinism, resulting from dysregulation of insulin secretion in patients with diffuse ABCC8 hyperinsulinism." (PMID 36398453, 2023).
Hyperglycemia (continued). "DM is a chronic metabolic disorder characterized by chronic hyperglycemia, resulting from defects in insulin secretion and/or insulin function." (PMID 37111299, 2023). "The placental tissue of women with GDM induces pro-inflammatory gene expression (tumor necrosis factor-α, TNF-α) that dysregulates insulin signaling and reduces insulin secretion from β-cells under the condition of hyperglycemia." (PMID 37239377, 2023). "After eight days of sleep disruption, rats presented hyperglycaemia and a reduction in insulin response after an intravenous glucose tolerance test; however, these animals also suffered a reduction in body weight without changes in food intake." (PMID 37571368, 2023). "In 3 out of 4 subjects, thiamine therapy allowed both normalization of hyperglycemia, with consequent insulin suspension, and macrocytic anemia." (PMID 38037112, 2023). "The alkaloids have been reported to regulate hyperglycemia via α-glucosidase and α-amylase inhibition, sensitizing insulin production, inhibition of PTP-1B and DPP-4 pathways, and managing oxidative stress condition." (PMID 37138848, 2023). "Post-challenge hyperinsulinemia is associated with a lower SgIo category, suggesting that SRH in these subjects is dependent on insulin excess in response to hyperglycemia." (PMID 36837857, 2023). "The proposed controller should avoid the risk of hyperglycemia and hypoglycemia situations that T1DP faces during the infusion of exogenous insulin." (PMID 37667042, 2023). "The viral and immune responses during critical stages of COVID-19 can also lead to hyperglycaemia and reduce insulin sensitivity, resulting in additional metabolic complications." (PMID 37511334, 2023). "This is better than the average waiting time of 4 hours before FDG administration after the use of rapid insulin for controlling hyperglycemia as per EANM guidelines." (PMID 37854083, 2023). "Despite the fact that INI only slightly affects glucose homeostasis in DM, its ability to increase insulin sensitivity and thereby alleviate hyperglycemia is gaining new evidence." (PMID 36834685, 2023). "Endothelin (ET) is found to be increased in kidney disease secondary to hyperglycaemia, hypertension, acidosis, and the presence of insulin or proinflammatory cytokines." (PMID 36834836, 2023). "STZ-induced hyperglycaemia was evident in both sexes, alongside impaired glucose tolerance and reduced insulin concentrations." (PMID 37650517, 2023). "DM is a carbohydrate-lipid metabolic disorder caused by insufficient insulin production, insensitivity to normal amounts of insulin, or both, resulting in abnormally high blood glucose levels (hyperglycemia, dysglycemia)." (PMID 38274772, 2023). "Inhibition of cullin neddylation rapidly decreases hepatic glucose generation, attenuates hyperglycemia and improves hepatic insulin signaling in mice." (PMID 37244925, 2023). "Treatment of streptozotocin diabetic rats with hesperidin reduced hyperglycemia, and increased serum and pancreatic insulin levels." (PMID 37008937, 2023). "In rodent studies, the administration of sirolimus worsened hyperglycaemia, abolished the hyperinsulinemic response and decreased muscle insulin sensitivity in diabetic animals." (PMID 36899932, 2023). "High concentrations of LDL-C are toxic in the pancreatic beta-cells and lead to impaired insulin secretion in the pancreas, and finally hyperglycaemia and T2D." (PMID 37795366, 2023). "Hypoglycemic agents, such as acarbose, miglitol, and voglibose, decrease PPG mainly by reducing the rate of carbohydrate digestion and gastrointestinal glucose uptake and improving hyperglycemia and insulin sensitivity in T2DM." (PMID 37895834, 2023). "Hyperglycemia alters the functions of vital trace elements such as zinc, which is required for insulin synthesis, storage, and the structural integrity of insulin." (PMID 37298118, 2023).
Hyperglycemia (continued). "The serum insulin test results revealed that the etiology of T1DM is islet β cell destruction, which leads to insufficient insulin secretion and hyperglycemia." (PMID 37504259, 2023). "It is a chronic metabolic disorder characterized by hyperglycemia resulting from defects in insulin secretion, insulin action, or both." (PMID 38022307, 2023). "DM is a group of physiological dysfunctions due to hyperglycaemia resulting directly from insulin resistance or inadequate insulin secretion." (PMID 36769565, 2023). "Given this evidence, surprisingly, the literature lacks a body of studies evaluating the effect of acute hyperglycemia on both macro and microvascular function during the control of plasma insulin concentrations." (PMID 36984870, 2023). "The application of insulin and other antidiabetic medications permits temporary reduction of systemic hyperglycemia promoted redifferentiation of dedifferentiated β-cells." (PMID 36875493, 2023). "Hyperglycemia-induced overproduction of reactive oxygen species (ROS) and vascular insulin resistance are key players in this state." (PMID 37433795, 2023). "On the other hand, other plant-derived compounds, fisetin, quercetin, morin, isoleucine, berberine, and berberrubine attenuated hyperglycemia in diabetic and obese animals by improving insulin sensitivity and/or inhibiting hepatic gluconeogenesis." (PMID 36986192, 2023). "T2DM is chiefly characterized by the decrease in insulin secretion or decreased sensitivity of target organs to insulin, which in turn leads to hyperglycemia, hyperlipidemia, and the increase in glucose production in the liver." (PMID 37601073, 2023). "Results from this study suggested that either low or high glucose effectiveness relates to hypoglycemia; in the first case, hypoglycemia would result from post-prandial hyperglycemia and hyperinsulinemia (insulin-dependent hypoglycemia)." (PMID 37726785, 2023). "After the diagnosis of hyperglycemia, a pregnant woman is referred to diet counseling, and if the blood glucose levels still exceed the target, metformin and/or insulin are usually indicated." (PMID 36982317, 2023). "No international threshold of hyperglycemia has yet been accepted for when to start insulin treatment, so hyperglycemia remains a challenge for neonatologists in terms of its definition and treatment." (PMID 37892314, 2023). "The primary outcome was beta-cell function as indicated by the late-phase disposition index (insulin secretion multiplied by insulin sensitivity) at steady-state hyperglycemia during a hyperglycemic clamp." (PMID 37127822, 2023). "The only unfavorable side effect found in the present study was that after perioperative glucocorticoid therapy, patients with AI developed postoperative hyperglycemia and required insulin infusion." (PMID 36676776, 2023). "IR is a condition characterized by the failure of insulin to provide the proper glucose transport from the bloodstream into the tissues, which results in the development of hyperglycemia and hyperinsulinemia." (PMID 37626790, 2023). "The investigators found that statin users had a higher likelihood to start insulin treatment, develop significant hyperglycaemia, and a need to increase additional glucose-lowering medication." (PMID 37795366, 2023). "The disorder is characterized by increased blood glucose levels (hyperglycemia), which is a result of insufficient production or improper function of insulin." (PMID 37408641, 2023). "Ectopic expression of Pdx1 induces sustained changes in hepatocytes, including activation of many specific pancreatic transcription factors and leads to production and secretion of insulin, which ameliorated hyperglycemia in STZ-induced diabetic mice." (PMID 38019818, 2023). "Maternal hyperglycemia in insulin-dependent diabetes during pregnancy enforces the fetal pancreas to release insulin that increases fetal and placental leptin concentration in paracrine and induces fetal overgrowth and macrosomia." (PMID 37854189, 2023).
Hyperglycemia (continued). "T2DM is a chronic metabolic disease manifested as hyperglycemia with insulin resistance (IR) or relatively inadequate insulin secretion." (PMID 37689643, 2023). "This is supported by the notion that hyperglycemia even in prediabetes is reflected by increased production of ROS and concomitant insulin resistance is tightly connected with increased oxidative stress." (PMID 37814622, 2023). "Oral amylase promotes the clear, direct, insulin-independent development of gut memory (an anti-incretin-acting memory that decreases hyperinsulinemia and depresses hyperglycemia)." (PMID 38003366, 2023). "The mechanisms of garlic are thought to improve hyperglycemia by increasing insulin secretion and enhancing insulin sensitivity." (PMID 37408757, 2023). "The destruction of β-cells results in the malfunction of insulin secretion and the reduction in glucose utilization by body tissues, which leads to hyperglycemia, liver injury, and kidney dysfunction." (PMID 37215365, 2023). "It was found that the average hospitalization time was 8.2 days (insulin infusion) and 10.4 days (subcutaneous insulin) in those with hyperglycemia." (PMID 37056543, 2023). "The primary goal of this study was to evaluate the effects of chronic hyperglycemia and immediate insulin treatment on the proportion of IL1β-immunoreactive (IR) myenteric neurons along the duodenum–ileum–colon axis." (PMID 36982878, 2023). "DM is a chronic, metabolic disease characterized by compromised insulin secretion, resistance to insulin action, or both, leading to hyperglycemia." (PMID 36839917, 2023). "Among the subsections of the DKS questionnaire, there was an average level of knowledge for the item “generalities” and a weak level for the other items (hypoglycemia, hyperglycemia, insulin treatment, SMBG)." (PMID 37777715, 2023). "Meanwhile, hinting at the important influence of CUL1 on cell metabolism, pharmacological inhibition of CUL1 neddylation has been reported to reduce hyperglycemia through sensitizing hepatic insulin signaling in mice." (PMID 37063418, 2023). "Oxidative injury of β-cells impairs mitochondrial ability to link glucose stimulus to insulin secretion in response to hyperglycemia, resulting in defective insulin production." (PMID 37463968, 2023). "It is characterized by hyperglycemia due to insufficient insulin secretion by pancreatic β-cells in response to overnutrition or insulin resistance." (PMID 36823211, 2023). "In addition, we suggest that liver SFA-related differences in DNA methylation profile may contribute more to hyperglycemia, while insulin-related differences are more linked to changes in methylation specific to NASH in this particular study population and setting." (PMID 36765383, 2023). "If the CBG is outside the target range, then either extra‐quick acting insulin to correct hyperglycaemia, or consumption of hypoglycaemia treatment to raise a low CBG is required." (PMID 36209371, 2023). "Pramlintide and insulin dual-hormone systems have been found to improve post-prandial hyperglycaemia when compared to an insulin-only HCL system." (PMID 37289734, 2023). "Whereas the mechanisms underlying the activation of these pathways remain to be elucidated, the more pronounced suppression of hepatic DNL or FAO, fed hyperglycemia, impaired hepatic insulin signaling, and metabolic stress are potential contributing factors." (PMID 37681411, 2023). "This condition, characterized by elevated blood sugar levels or hyperglycemia, results from abnormal insulin secretion and/or action." (PMID 38146555, 2023). "They used a grade 2 or higher as their cut-off, indicating patients had received insulin or other medications to treat the hyperglycemia." (PMID 40303251, 2023). "The regulation of caloric intake is essential in the maintenance of insulin sensitivity, body weights and hyperglycaemia in metabolic disorders." (PMID 38096150, 2023).
Hyperglycemia (continued). "The current medications can lessen the harm to the body brought on by hyperglycemia by regulating blood sugar levels and increasing insulin sensitivity." (PMID 36904097, 2023). "miRNAs are regulators of adipogenesis, which involves processes such as hyperglycemia or insulin regulation." (PMID 36839169, 2023). "Unfortunately, clinical guidelines do not explicitly provide recommendations on the optimal route and type of insulin therapy for PN-related hyperglycemia, and there is little literature comparing the efficacy and safety of these regimens." (PMID 37674887, 2023). "Insulin resistance impairs this signaling pathway and results in hyperglycemia as these normally insulin-sensitive tissues instead use fatty acids as a fuel source." (PMID 37242739, 2023). "In GCK-MODY pregnancies, the insulin secretory response to maternal hyperglycaemia is dependent on the fetal genotype." (PMID 37653058, 2023). "Arachidonic acid (AA)-rich ARASCO oil reduces hyperglycaemia, restores insulin sensitivity, inhibits inflammation, increases plasma lipoxin A4 levels and restores the altered antioxidant status of HFD + STZ-induced diabetic animals to near normal." (PMID 37600949, 2023). "Together, the data indicate that OPG treatment increases and maintains normal serum insulin levels in the mice, thus improving hyperglycemia." (PMID 37910614, 2023). "Due to the observational nature of the study, not all data were available for all patients, and we were unable to control for all factors possibly interfering with glucose levels, including the daily amount of insulin units used to correct hyperglycemia." (PMID 37193970, 2023). "Despite marked hyperglycaemia, impaired insulin secretion and paradoxical glucagon elevation were observed in high-fat diet-fed Gls2 CKO mice." (PMID 37147373, 2023). "The incorrect estimation of the DIA induces mismatch in the IOB and insulin injection, thereby resulting in hypoglycemia or hyperglycemia." (PMID 36793281, 2023). "Enhanced plasma insulin levels further help to improve hyperglycemia-induced dyslipidemia through transcriptional modulation of hepatocytes." (PMID 37110174, 2023). "There is a general consensus that T2DM is characterized by chronic hyperglycemia resulting from impaired insulin secretion and altered glutathione metabolism, and mitochondrial dysfunction in adipose tissue partially participates in the pathogenesis of T2DM." (PMID 37700362, 2023). "Hyperglycemia can also increase the production of reactive oxygen or nitrogen species and counteracts insulin activity in the human body." (PMID 37324871, 2023). "The bedtime insulin daytime SU therapy uses insulin dosing based on the pathophysiology of fasting hyperglycemia in patients with T2DM." (PMID 36624650, 2023). "Mice with the elevated expression of a major antioxidant selenoprotein (GPX1) showed hyperglycemia, hyperinsulinemia, elevated body fat accretion and plasma leptin and reduced insulin sensitivity." (PMID 36978903, 2023). "There is no definitive answer to the question of what stimuli other than hyperglycemia are necessary to induce insulin synthesis in the liver." (PMID 38019818, 2023). "In contrast, insulin has a counter-regulatory effect by reducing high blood glucose levels (hyperglycemia)." (PMID 37762083, 2023). "Stage 2 is marked by further destruction of pancreatic β-cells, leading to a progressive decline in insulin production and hyperglycemia." (PMID 38094298, 2023). "db/db mice with PAX6 replenishment displayed a long‐term improvement in hyperglycemia and elevated serum insulin level with an overall trend up to 5 months compared to db/db mice receiving AAV‐Ctrl." (PMID 37933577, 2023). "Correlating with reduced maternal insulin sensitivity, and in response to hyperglycaemia, AT and the placenta secrete exosomes containing apolipoproteins implicated in the complement and coagulation cascade and cholesterol metabolism." (PMID 38288471, 2023).